EGFR (epidermal growth factor receptor)
Diseases named in the same sentence as EGFR in open-access papers (continued):
Sharing a sentence is not in itself a finding about the gene and the disease.
cancer (continued). "Recently, epidermal growth factor receptor (EGFR)-targeted therapy has been introduced as an alternative therapeutic strategy for highly malignant cancers." (PMID 15785737, 2005). "Epidermal growth factor receptor is a promising target for cancer therapy and a number of anti-EGFR agents have been developed." (PMID 15841081, 2005). "Simultaneous overexpression of both HER2 and HER3 was found in several cancers, and increased drug resistance in many HER2-overexpressing cancers depends on increased levels of HER3 or EGFR." (PMID 16288303, 2005). "Despite mixed results in cancer treatment, many dysplastic cells also have activated EGFR and are reasonable targets for these agents." (PMID 16160697, 2005). "Drug-resistant cancer cells exhibited elevated level of EGFR expression, while drug-sensitive germline cells showed a lower EGFR expression." (PMID 15655552, 2005). "In view of the crucial importance of the EGFR-mediated signalling cascade to cancer therapeutics, this receptor has been the focus of intense research." (PMID 15611794, 2005). "Among the recent advances in the molecular targeted therapy of cancer, the applications focused on EGFR are currently the most promising and the most advanced at clinical level." (PMID 15756277, 2005). "Some of the current targeted therapies attempt to localise drugs to cancer cells based on overexpression of epidermal growth factor receptors (EGFR) or angiogenesis." (PMID 15685239, 2005). "In fact, cancer cells expressing higher levels of EGFR were much more resistant to the growth inhibitory effect of DNA-damaging agents than were control cells." (PMID 15655552, 2005). "Epidermal growth factor receptor (EGFR) is one of the most appropriate target molecules for cancer therapy because of its relatively high expression in about one-third of all epithelial cancers in correlation with neoplasmic progression." (PMID 15083186, 2004). "Since its identification, the epidermal growth factor receptor (EGFR) has emerged as a significant factor in the development and growth of many types of cancers." (PMID 14710211, 2004). "A line of evidence that the EGFR plays a role in the pathogenesis of various cancers has led to the rational design and development of agents that selectively inhibit this receptor." (PMID 15083186, 2004). "Epidermal growth factor receptor signalling is critical not only for cell proliferation but also in other processes crucial to cancer progression, and EGFR is therefore a target for anticancer therapies." (PMID 15083203, 2004). "It is now accepted that the EGFR signal transduction network plays an important role in multiple tumorigenic processes, contributing to cancer-cell proliferation, angiogenesis, and metastasis, as well as protection from apoptosis." (PMID 14710211, 2004). "Gefitinib is the first EGFR agent to be approved for cancer treatment in Japan, the USA and other countries." (PMID 14760365, 2004). "Since the majority of NSCLC expresses EGFR, this represents a rational target for novel agents that can block cancer cell growth by interfering with this mitogenic signalling pathway." (PMID 14710211, 2004). "Gefitinib (Iressa, ZD1839) is an orally active EGFR-tyrosine kinase inhibitor (TKI) that blocks signal transduction pathways implicated in proliferation and survival of cancer cells." (PMID 14710235, 2004). "Gefitinib (ZD1839, IRESSA, Astrazeneca, London, UK) is an orally active, selective EGFR tyrosine-kinase inhibitor (TKI) that blocks signal transduction pathways implicated in the proliferation and survival of cancer cells." (PMID 14710211, 2004). "Recent studies have suggested that gefitinib induces cell cycle retardation and apoptosis, and inhibits the growth of several types of human cancer cells expressing EGFR both in vitro and in vivo." (PMID 14710235, 2004). "Much of the work on the EGFR in the lung has been performed in the context of cancer, where elevated EGFR expression is a frequent observation." (PMID 15340376, 2004).
cancer (continued). "The epidermal growth factor receptor (EGFR) is a promising target for cancer therapy and a number of EGFR-targeted agents have been developed." (PMID 14760365, 2004). "EGFR and Her-2 proteins were measured in 59 paired (grossly normal and cancer) tissues by an enzyme immunoassy method." (PMID 12915878, 2003). "Inhibiting EGFR and their specific TK activity is regarded as a very promising approach for innovative therapeutic strategies in cancer treatment." (PMID 14583782, 2003). "Recently, evidence has been accumulated indicating that the epidermal growth factor receptor (EGFR) is a promising target for novel cancer therapy." (PMID 14583782, 2003). "The tyrosine kinase receptor, epidermal growth receptor (EGFR) family proteins EGFR and Her-2 have been reported to be overexpressed in many cancers." (PMID 12915878, 2003). "The epidermal growth factor receptor (EGFR) autocrine pathway contributes to a number of processes important to cancer development and progression, including cell proliferation, apoptosis, angiogenesis, and metastatic spread." (PMID 14612886, 2003). "We analyse EGFR and Her-2 protein levels in the paired grossly normal mucosa and cancer tissues obtained from the same patients." (PMID 12915878, 2003). "Gefitinib (‘Iressa’, ZD1839) is an orally active, epidermal growth factor receptor (EGFR) tyrosine kinase inhibitor that blocks signal transduction pathways implicated in the proliferation and survival of cancer cells." (PMID 14661048, 2003). "The development of compounds such as IMC-C225, an EGFR monoclonal antibody, or ZD1839 (‘Iressa’), an orally active, selective EGFR tyrosine kinase inhibitor, is representative of this new therapeutic strategy for the treatment of cancer." (PMID 11986789, 2002). "The EGFR and its respective ligands such as TGFα trigger growth and prevent apoptosis by autocrine and/or paracrine mechanisms in many cancer cell lines." (PMID 11953870, 2002). "The primary carcinoma-derived cells had up to three-fold higher total EGFR levels than the Caco-2 subclones and a basal mitotic rate at least fourfold higher." (PMID 9667648, 1998). "A series of low molecular weight molecules have been identified which inhibit the EGFR PTK in vitro and demonstrate antiproliferative activity against human cancer cell lines with high expression of EGFR." (PMID 8956783, 1996). "In contrast, analysis of 44 primary cancers showed, in agreement with the literature, a significant inverse relationship between the presence of ER and EGFR (Fisher's exact test P less than 0.002)." (PMID 2803944, 1989). "Furthermore, we only targeted EGFR as it is an important cancer therapeutic target, but this protein has its own pattern of regulation." (PMID 41334459, 2026). "Integrative analyses of patient tissue samples, cellular models, an animal model, and cancer databases highlight the critical role of the LAPTM4B-ATP1A1-lysosomal acidification axis in EGFR-TKI resistance, providing a promising therapeutic avenue for overcoming resistance in EGFR-mutant NSCLC." (PMID 41362742, 2026). "Overall, thiazine derivatives represent viable scaffolds for EGFR-targeted anti-cancer development; however, further optimization and experimental validation, including biochemical assays and genotoxicity testing, are required to confirm their therapeutic potential." (PMID 41552637, 2026). "Targeting the EGFR pathway may lead to the activation of the MET or HER2 pathways, offering an escape mechanism for cancer cells and diminishing the efficacy of EGFR inhibitors." (PMID 41562920, 2026).
cancer (continued). "Furthermore, we found that truncation of PTCH1 C-tail upregulated several cancer-related pathways, including EGFR and Ras signalling and led to enhanced GLI-dependent PI3K activation, which exerted a positive feedback regulation on GLI expression and activity." (PMID 41748949, 2026). "Another cancer-associated gene that was differentially expressed in the RNA-seq experiment but was not listed in the pathways in cancer list is EGFR." (PMID 41467516, 2026). "We next investigated whether the inhibitory effects of sorafenib on the emergence of resistance are specific of EGFR-addicted cancer cells." (PMID 40846697, 2025). "Moreover, EGFR translocation on mitochondria has been observed in response to stress signals, suggesting a potential mechanism for drug resistance in cancer therapy." (PMID 41145430, 2025). "Gene sets related to EGFR signaling were notably enriched in patients with elevated USP11 expression, along with ten other gene sets associated with cancer-related modules." (PMID 41419456, 2025). "This approach could be particularly valuable in cancers that lack EGFR/HER2 amplification but are highly reliant on DNA repair for survival." (PMID 41208896, 2025). "Notably, the epidermal growth factor receptor (EGFR) mutation was positive, identifying the cancer as non-small-cell lung cancer (NSCLC)." (PMID 40556846, 2025). "Furthermore, cancer cell-derived EVs containing oncogenic EGFR were able to transfer this receptor to primary endothelial cells in vitro and in vivo, resulting in the onset of autocrine VEGF production and phosphorylation of VEGFR2." (PMID 40563616, 2025). "EGFR has a close relationship with the occurrence, development, and treatment of cancer." (PMID 40573220, 2025). "In addition, Cathepsin S and EGFR were also upregulated in cancer secretomes in comparison to control samples." (PMID 39743544, 2025). "However, recent studies have revealed that EGFR can also translocate from plasma membrane into the mitochondria, influencing cellular metabolism, apoptotis and drug resistance in cancer cells." (PMID 41145430, 2025). "Moreover, EGFR (epidermal growth factor receptor) is an important kinase that is involved in cancer cell growth." (PMID 41154723, 2025). "Cancer-associated fibroblasts (CAFs) are a major source of HGF, which can sustain MET signaling in a paracrine manner, leading to persistent oncogenic activation even in the presence of EGFR-TKIs." (PMID 40365349, 2025). "To further evaluate our findings, and to promote the clinical translation of our study, we developed a highly multiplexed targeted proteomics assay for 90 proteins associated with cancer metabolism, RNA regulation, and signature cancer pathways, such as PI3K/AKT/mTOR and EGFR/RAS/RAF." (PMID 39723668, 2025). "The KEGG pathway analysis determined that the DEPs were enriched in several other pathways in addition to the cytokine–cytokine receptor interaction pathway, including the pathways for PI3K–Akt, MAPK, and RAS signaling, proteoglycans in cancer, and EGFR tyrosine kinase inhibitor resistance." (PMID 41244106, 2025). "Moreover, collagen type I has been shown to induce resistance by activating mTOR signaling through an Akt-independent mechanism, fostering the survival and proliferation of EGFR-mutant cancer cells." (PMID 40002883, 2025). "Thereover, targeting EGFR suppresses cancer cell proliferation." (PMID 41210686, 2025). "Recently, several EGFR inhibitors have been developed for cancer therapy." (PMID 40165104, 2025). "As a matter of fact, the improvements of DNA cloning in the 1980s and 1990s allowed to isolate several genes related to the EGF receptor (EGFR), and to connect the dysregulation of these genes to many different cancers, including lung, breast, and gastrointestinal tract malignancies." (PMID 39470386, 2025).
cancer (continued). "Previous studies have highlighted the involvement of other RTKs in the response to EGFR inhibitors in cancer, including human epidermal growth factor receptor 2 (HER2), human epidermal growth factor receptor 3 (HER3), and MET (also known as hepatocyte growth factor receptor or HGFR)." (PMID 41514577, 2025). "Modifications to the EV surface, such as the addition of specific ligands or antibodies, can help direct these vesicles to target tissues or organs more effectively, such as the RVG peptide, that drives EVs to CNS, or antibodies like anti-EGFR, which can target drugs to cancer cells." (PMID 39860010, 2025). "Compounds 7j, 7k, and 7o (GI50 values of 27, 25, and 30, respectively) demonstrated greater potency than erlotinib (GI50 value of 33 nM), particularly against breast (MCF-7) cancer cell lines, and were identified as the most potent dual EGFR/VEGFR-2 inhibitors." (PMID 40556275, 2025). "EGFR, already recognized for its proliferative role, may also contribute to reduced cancer cell motility upon suppression." (PMID 41411347, 2025). "EGFR plays a fundamental role in cancer biology and especially NSCLC biology." (PMID 40601773, 2025). "Lastly, we examined whether the SR-Coa/ethyl azidoacetatesystem can degrade EGFR in vivo in a subcutaneous cancer model." (PMID 39805770, 2025). "Moreover, MUC4 has distinct extracellular and cytoplasmic tail domains that work together to promote EGFR signaling, which is essential for cancer cell behaviors such as invasion and metastasis." (PMID 40655139, 2025). "E-EDV-D682 is targeted directly to cancer cells via an anti-EGFR antibody." (PMID 39373598, 2025). "Compared to EGFR, cancer cells rely more on AXL for downstream pro-survival signaling in TNBC." (PMID 40560045, 2025). "Therapeutic techniques targeting EGFR remain the mainstay of treatment for advanced cancers, and this preclinical study may influence future treatment options for SCCHN." (PMID 40535810, 2025). "EGFR might promote cancer development by activating IRE1a-XBP1s signaling and related EGFR targeting enhances chemotherapy efficiency." (PMID 40478912, 2025). "To date, fourteen EGFR-targeting agents have been approved for cancer treatments." (PMID 39940134, 2025). "Epidermal growth factor receptor (EGFR) is a transmembrane protein that plays a key role in cell signaling pathways involved in cell growth, proliferation, and survival and is often overexpressed or mutated in various cancers." (PMID 40182844, 2025). "Therefore, molecular pathways characterizing intestinal-type tumors, together with other cancer-related pathways, are involved in cell cycle regulation and the response to growth factors and hormones (EGFR, estradiol, and progesterone)." (PMID 40361332, 2025). "Whether serum CEACAM5 fluctuations reflect EMT and rEMT in primary tumors and metastatic sites to enable cancer cell dissemination and proliferation under EGFR‐TKI treatment and latter drug resistance requires further investigation." (PMID 40856433, 2025). "In cancer, EGFR overexpression is mostly due to EGFR gene amplification or mutations." (PMID 41227364, 2025). "NFκB is activated by the EGF/EGFR pathway, contributing to inflammation and cancer progression." (PMID 40292295, 2025). "The groundbreaking advancements in cancer treatment have been greatly aided by EGFR TKIs and mAbs." (PMID 40535810, 2025). "In wild-type EGFR-expressing cancer cells, mechanisms of the resistance to gefitinib remain largely unknown." (PMID 40560045, 2025). "The effects of EGFR signalling on cancer glucose metabolism may be driven through the PI3K/AKT/mTORC1 pathway, mTORC2, the transcription factor c-Myc, PKM2 phosphorylation, or stabilisation of the sodium/glucose cotransporter 1 (SGLT1)." (PMID 39433211, 2025). "The treatment of EGFRm‐related cancer has centered on the key factor, EGFR." (PMID 39994841, 2025).
cancer (continued). "Furthermore, co-culturing immature dendritic cells with dying cancer cells targeted by EGFR and TF NIR-PIT agents mediated enhanced dendritic cell maturation, as indicated by increased expression of CD80, CD86, CD40, and HLADR." (PMID 41362788, 2025). "Of note, the targets of DDAs were initially unknown, thus, optimization of their potency and selectivity was based on their ability to selectively kill cancer cells overexpressing EGFR or HER2." (PMID 40867591, 2025). "This provides a route for cancer cells to resist EGFR inhibition and promotes cell survival." (PMID 40560045, 2025). "EGFR is a key target in cancer therapy due to its role in cell growth." (PMID 40721411, 2025). "Additionally, combination strategies integrating EGFR inhibitors with immune checkpoint blockades are being actively investigated to enhance therapeutic outcomes in resistant and refractory cancers." (PMID 40943615, 2025). "Notably, the most significantly enriched KEGG pathways included neuroactive ligand-receptor interaction, pathways in cancer, EGFR tyrosine kinase inhibitor resistance, PI3K-Akt signaling pathway, MAPK signaling pathway, and calcium signaling pathway." (PMID 40800999, 2025). "Furthermore, the dose-dependent nature of H1975 cell death provides valuable insights for developing effective and safe therapies to overcome EGFR-TKI resistance in future cancer treatments." (PMID 40076971, 2025). "This pattern of ERBB2 and EGFR co-expression in a subset of cancer cells may be of clinical significance as elevated EGFR expression can promote T-DXd resistance by suppressing T-DXd internalization." (PMID 41422272, 2025). "Furthermore, EGF nanoparticles exhibited high cytotoxicity against cancer cells responding poorly to conventional EGFR-targeted anti-cancer drugs, showing potential for future medical applications." (PMID 41140511, 2025). "In addition, we discovered that the activation of both WT and L858R mutant EGFR is contingent upon ER export, highlighting the inhibition of EGFR ER export as a viable strategy for targeting EGFR-related cancers." (PMID 40449599, 2025). "Furthermore, pVHL regulates cancer cell proliferation by targeting epidermal growth factor receptor (EGFR), retinol binding protein 1 (RBP1), and protein kinase C (PKC)." (PMID 40576306, 2025). "KEGG analysis indicated that the drug combination might work through pathways like PI3K-Akt signaling, microRNAs in cancer, and EGFR tyrosine kinase inhibitor resistance." (PMID 39863836, 2025). "Furthermore, it is imperative to consider the implications of EGFR inhibition, which is commonly used in cancer therapy and can induce dermatological toxicities such as papulopustular rashes." (PMID 40564048, 2025). "Notably, over half of the druggable proteins were found to be targets for multiple drugs, with EGFR for example being targeted by 56 phase 1–4 drugs, of which 20 are approved therapeutics for the treatment of various cancer types." (PMID 40225784, 2025). "It is also used in combination with irinotecan to treat cancers with overexpression of EGFR." (PMID 40943615, 2025). "EGFR is a critical biomarker for cancer diagnosis and therapy." (PMID 40906195, 2025). "The Japan Clinical Cancer Research Organization (JACCRO) has reported positive effects of re-administration of anti-EGFR antibody drugs (Cmab: JACCRO-CC08 and Pmab: JACCRO-CC09); however, these reports only referred to side effects at the time of re-administration." (PMID 40755575, 2025). "As there were differences in the EGFR scores of cancer patients with different immunotherapy responses, we hypothesized that the evaluation of EGFR.Sig expression levels could predict the efficacy of immunotherapy to some extent." (PMID 40574864, 2025). "Numerous targeted cancer therapies have been developed against EGFR." (PMID 40259338, 2025).